ARHGEF17 (Rho guanine nucleotide exchange factor 17)
Description:
Acts as a guanine nucleotide exchange factor (GEF) for RhoA GTPases.
Synonyms: p164-RhoGEF; p164RhoGEF; KIAA0337; TEM4; RHOGEF17
Tractability: Antibody: the Human Protein Atlas places it where antibodies can reach. PROTAC: ubiquitination databases record sites on it; its protein half-life has been measured.
Gene: Protein-coding gene on chromosome 11 (73,308,276 to 73,369,388, forward strand). Ensembl gene ENSG00000110237.
Subcellular location (Human Protein Atlas): Cytosol; Plasma membrane
Pathways (Reactome):
Signal Transduction: G alpha (12/13) signalling events; NRAGE signals death through JNK; RHOA GTPase cycle; RHOB GTPase cycle; RHOC GTPase cycle
Gene Ontology:
Molecular function: guanyl-nucleotide exchange factor activity; protein binding
Biological process: actin cytoskeleton organization; regulation of small GTPase mediated signal transduction
Cellular component: cytoplasm; cytosol
Genetic constraint (gnomAD): Loss-of-function variants: 80 observed, 168.92 expected, observed/expected ratio (o/e) 0.47, 90% interval 0.39 to 0.57. The upper end of that interval is the gene's LOEUF score, 0.57, which puts it in group 2 of 6, group 1 being the genes least tolerant of losing a copy. Missense variants: 2,886 observed, 2,804 expected, observed/expected ratio (o/e) 1.03, 90% interval 1 to 1.06. Synonymous variants: 1,311 observed, 1,165.6 expected, observed/expected ratio (o/e) 1.12, 90% interval 1.07 to 1.18.
Homologues: Orthologues: chimpanzee ARHGEF17 (99% identical), macaque ARHGEF17 (96% identical), dog ARHGEF17 (91% identical), mouse Arhgef17 (87% identical), rat Arhgef17 (86% identical), rabbit ARHGEF17 (82% identical), guinea pig ARHGEF17 (78% identical), tropical clawed frog arhgef17 (51% identical), zebrafish arhgef17 (32% identical), Caenorhabditis elegans osg-1 (18% identical). Paralogues in human: ARHGEF10L (14% identical), ARHGEF10 (14% identical).
Diseases named in the same sentence as ARHGEF17 in open-access papers:
ARHGEF17 is named in the same sentence as 17 diseases in open-access papers, as found by Europe PMC text mining. Sharing a sentence is not in itself a finding about the gene and the disease. The quoted sentences say what the papers report.
intracranial aneurysm (3 papers, 2021 to 2022). "Our report expands the phenotypic spectrum of ARHGEF17 variants from increased intracranial aneurysm risk to neurodevelopmental disease and thereby add ARHGEF17 to the list of GEF genes involved in neurodevelopmental disorders." (PMID 36341116, 2022). "Using next generation sequencing (NGS), bioinformatics, and ARHGEF17-deficient zebrafish, our research group found that ARHGEF17 is a candidate gene for intracranial aneurysm (IA)." (PMID 35047576, 2021). "In line with this, ARHGEF17 has been recently linked as a risk gene to intracranial aneurysms." (PMID 36341116, 2022).
colon cancer (2 papers, 2021 to 2022). "Mutations on ARHGEF17 contributed to the lung metastasis from colon cancer." (PMID 35795065, 2022). "ARHGEF17 was involved in Phospholipase C signaling, which contributed to the lung metastasis from colon cancer." (PMID 35795065, 2022). "ARHGEF17 (Rho Guanine Nucleotide Exchange Factor 17) contributes to the lung metastasis from colon cancer via participation in “phospholipase C signaling”." (PMID 35795065, 2022).
lung carcinoma (2 papers, 2018 to 2022). "Herein, using immunocompetent mice and a syngeneic lung cancer cell line, we demonstrate that ARHGEF17 is indeed involved in tumor growth and metastasis and revealed how Gβγ activates this RhoGEF." (PMID 34808208, 2022). "To get an initial insight into the potential role of ARHGEF17 in lung cancer we looked for clinical differences in patients having this gene amplified compared with all others." (PMID 34808208, 2022). "Together, these results suggest that ARHGEF17 plays a critical role in lung cancer growth and metastatic dissemination." (PMID 34808208, 2022). "Here, we demonstrate that ARHGEF17, component of a transcriptional signature predictive for reduced survival in various cancers, is involved in invasion and migration of lung cancer cells elicited by Gi-coupled LPARs." (PMID 34808208, 2022). "Specifically, we addressed the hypothetical role of ARHGEF17, a RhoGEF, as a potential effector of Gβγ in metastatic lung cancer cells responding to LPA." (PMID 34808208, 2022). "Here, we show that ARHGEF17, originally identified as a tumor endothelial marker, is involved in tumor growth and metastatic dissemination of lung cancer cells in an immunocompetent murine model." (PMID 34808208, 2022). "We used immunocompetent mice as a preclinical model to address the involvement of ARHGEF17 in tumorigenesis by syngeneic LAP0297 lung cancer cells and established the mechanism by which Gi-coupled LPARs activate this RhoGEF." (PMID 34808208, 2022). "Since increased expression of ARHGEF17 correlated with bad prognosis in lung cancer patients with high-grade tumors, here we analyzed its role in tumor growth and metastasis." (PMID 34808208, 2022). "Gene expression–based analysis of lung cancer datasets showed that increased levels of ARHGEF17 correlated with reduced survival of patients with advanced-stage tumors." (PMID 34808208, 2022). "These analyses were consistent with a hypothetical role of ARHGEF17 in lung cancer progression." (PMID 34808208, 2022). "Given the reduced tumorigenic and metastatic power of ARHGEF17-knockdown cells, we explored the cellular and molecular mechanisms by which ARHGEF17 might play a critical role in lung cancer." (PMID 34808208, 2022). "In conclusion, ARHGEF17 plays an important role in tumor growth and dissemination, which together with the reduced survival of lung cancer patients with advanced disease and high ARHGEF17 expression, are consistent with a pathological role of ARHGEF17 in metastatic cancer." (PMID 34808208, 2022). "The presence of Gβγ in the active fraction of ARHGEF17 supported a potential mechanistic link between these signaling proteins relevant to drive actin cytoskeleton reorganization and cell migration in lung cancer cells responding to LPA." (PMID 34808208, 2022). "To directly address the potential role of ARHGEF17 in metastatic lung cancer, we knocked down this RhoGEF in LAP0297 lung cancer cells using a lentiviral shRNA-ARHGEF17 to address their tumorigenic and organotropic metastatic potential in immunocompetent FVB mice." (PMID 34808208, 2022). "Altogether, these results revealed the critical role played by ARHGEF17 in the migratory and invasive response of metastatic LAP0297 lung cancer cells to LPA." (PMID 34808208, 2022).
aneurysm (1 paper, 2022). Bulging or ballooning in an area of an artery secondary to arterial wall weakening. "Here we report siblings of a consanguineous Pakistani family with biallelic variants in the ARHGEF17 gene associated with a neurodevelopmental disorder with intellectual disability, speech delay and motor dysfunction but not aneurysms." (PMID 36341116, 2022).
intracranial haemorrhage (1 paper, 2022). "Similar to IA-associated Rho-GTPase ARHGEF17, of which pathogenic variants cause intracranial haemorrhage in zebrafish, this could indicate that IA formation or rupture is mediated through actin-dependent smooth muscle cell action." (PMID 35228681, 2022).
Lewis lung carcinoma (1 paper, 2022). "In this regard, ARHGEF17 (also known as TEM4/p164-RhoGEF), a RhoGEF potentially linked to tumor-induced angiogenesis, has been found overexpressed in murine Lewis lung carcinoma tumors." (PMID 34808208, 2022).
metastatic cancer (1 paper, 2022). A carcinoma which has spread from the original site of growth to another anatomic site. "Our results highlight ARHGEF17 as a relevant effector and potential target for therapeutic strategies in metastatic cancer." (PMID 34808208, 2022).
nasal polyps (1 paper, 2012). "More interestingly, two genes (RUNX3 and ARHGEF17) can function as tumor suppressor genes, and neither of these two genes has been previously investigated in the pathogenesis of nasal polyps." (PMID 23185289, 2012).
tumor (10 papers, 2012 to 2025). "Across the tumor samples, increased expression of ARHGEF17 is associated with increased YAP activity and increased sensitivity to loss of the YAP gene and interestingly is linked with decreased sensitivity to methotrexate." (PMID 34010657, 2021). "Depletion of Arhgef2 (GEF-H1) and Arhgef17 (Tumour Endothelial Marker 4, TEM4) resulted in a reduced lamellipodia protrusion speed similar to that seen with TRPV4 inhibition." (PMID 40196692, 2025). "Given that chemotactic GPCRs are well-recognized promoters of tumor growth and dissemination, our findings place ARHGEF17 within the repertoire of relevant signaling effectors in oncogenic settings." (PMID 34808208, 2022). "We focused on ARHGEF17 given its original identification as a tumor endothelial marker and target of the Hippo pathway." (PMID 34808208, 2022). "The RhoGEF17 gene (ARHGEF17) was initially found to be up-regulated during angiogenesis in human tumor endothelium." (PMID 33801779, 2021). "In the tumor patient samples, cancer cell lines, and direct knockdown experiments, the levels of ARHGEF17 were positively correlated with the transcriptional activity of YAP." (PMID 34010657, 2021). "Although ARHGEF17 was originally identified as a tumor endothelial transcript, its potential role in cancer progression remains unknown." (PMID 34808208, 2022). "In addition, catalytic-independent functions of ARHGEF17, including its ability to control a mitotic checkpoint, might also play a role in tumor growth, which deserves further investigation." (PMID 34808208, 2022). "Given the central role played by Rho GTPases at various stages of tumor progression, our studies set the ground for future investigations aiming to address whether ARHGEF17 is a common effector of Gβγ-dependent signaling pathways elicited by chemotactic GPCRs within the tumor microenvironment." (PMID 34808208, 2022). "These experiments together indicate that coincidental TGFß and AP-1 signaling are required for Arhgef17, RhoA, and MRTF activation that leads to non-canonical Hh signaling and tumor resistance." (PMID 33033234, 2020).
cancer (5 papers, 2013 to 2022). A tumor composed of atypical neoplastic, often pleomorphic cells that invade other tissues. "Since cell migration and proper control of the cell cycle are altered in cancer cells, the finding that ARHGEF17 is mechanistically linked to these essential processes is consistent with a putative dysregulation of this RhoGEF in carcinogenesis and metastasis." (PMID 34808208, 2022). "Interestingly, the expression of ARHGEF17 is regulated by the Hippo pathway, and it is part of a transcriptional signature that, together with 21 other genes, shows prognostic value among various cancer types." (PMID 34808208, 2022). "Indeed, ARHGEF17 was previously reported to be directly involved in mitosis and the expression of ADAM9 was associated with the progression and resistance of several cancer types." (PMID 35251951, 2021).
ARHGEF17 also shares sentences with these, for which no sentence is quoted: bacterial infection (1 paper); colorectal cancer (1); Intellectual disability (1); liver cancer (1); neurodevelopmental disorder (1); pancreatic cancer (1); schizophrenia (1).